IRX5 (iroquois homeobox 5)
Diseases named in the same sentence as IRX5 in open-access papers (continued):
Sharing a sentence is not in itself a finding about the gene and the disease.
hypospadias (3 papers, 2019 to 2025). Hypospadias is the displacement of the urethral meatus on the ventrum of the penis. "In patient 5, six variants in six genes were found: BNC2, FGF10, HSD3B2, IRX5, MAML2 and NOTCH2; all, except MAML2, have also been associated with hypospadias or gonadal development." (PMID 31555317, 2019). "It is reported that SNP loci located in other homologous gene box families (such as HOXA cluster, IRX3, IRX5, ZFHX3, etc.)also increase the risk of hypospadias, which may suggest the focus of the future research." (PMID 40547448, 2025). "Although we did not include all possible proteins encoded by hypospadias risk associated genes (for example IRX5, IRX6, EYA1) for PPIs, our investigations indicated that disruption of SP1 and SP7 activity is associated with multiple known hypospadias risk associated genes in human via PPIs." (PMID 31856834, 2019).
colon cancer (2 papers, 2008 to 2020). "MiR-136-5p was found to inhibit cell proliferation, migration and invasion in renal cell carcinoma, liver cancer - by regulating IRX5, and in colon cancer, through targeting LRH-1/Wnt signaling." (PMID 32074085, 2020). "In a panel of 20 colon cancer cases, all these genes except IRX5, TFAP2E and TFAP2C showed significantly higher methylation in cancer by t-test analysis (P<0.001 for NKX2-5, DPYS SPOCK2, GALR2 and SLC16A12; P = 0.008 for FOXN4)." (PMID 18446232, 2008).
liver cancer (2 papers, 2020 to 2024). An epithelial or non-epithelial malignant neoplasm that arises from the liver. "Whether its roles in tumorigenicity or anti-apoptosis are related to ADCP remains unknown, and further investigation is needed to determine if IRX5 enhances the malignant capabilities of liver cancer cells by conferring resistance to ADCP." (PMID 38774870, 2024).
Osteopenia (2 papers, 2022 to 2025). Osteopenia is a term to define bone density that is not normal but also not as low as osteoporosis. "A recent study showed that mice with global KO of either IRX3 or IRX5 exhibit osteopenia, a precursor state of osteoporosis, with impaired osteoblast differentiation and increased bone marrow adipogenesis." (PMID 40769964, 2025).
tongue squamous cell carcinoma (2 papers, 2018 to 2019). A squamous cell carcinoma that arises from the tongue. "In tongue squamous cell carcinoma, overexpression of IRX5 was found to contribute to proliferation, migration, and invasion of cancer cells via activation of the NF-kB pathway and interactions with osteopontin." (PMID 31475119, 2019). "In this study, we observed that IRX5 was abnormally abundant in tongue squamous cell carcinoma (TSCC) tissues and cell lines." (PMID 29761910, 2018).
atrophic gastritis (1 paper, 2023). "Downregulation of IRX5 was observed in H. pylori-positive atrophic gastritis compared with normal gastric mucosal tissues, indicating that H. pylori infection, one of the most important gastric cancer risk factors, is also related to IRX5 expression regulation." (PMID 36980893, 2023).
breast-invasive carcinoma (1 paper, 2023). "Consistent with BRCA1 being a downstream target of IRX5, there was significant correlation between BRCA1 and IRX5 gene expression in breast-invasive carcinoma, suggesting that the regulatory relationship between IRX5 and BRCA1 extends beyond epidermal keratinocytes." (PMID 37084727, 2023).
diabetic cardiomyopathy (1 paper, 2013). Diabetic cardiomyopathy is a disorder of the heart muscle in people with diabetes. "The data presented here clearly shows that Kv4.2 modulation is independent of Irx5 and therefore microRNA mediated regulation may be important for better understanding of diabetic cardiomyopathy." (PMID 23573265, 2013).
gastric adenocarcinoma (1 paper, 2023). "Furthermore, in the MKN45 cell line (established from a poorly differentiated gastric adenocarcinoma), IRX5 (IRX-2a) expression was found to be upregulated after treatment with H. pylori water extract." (PMID 36980893, 2023).
gastric cancer (1 paper, 2023). A primary or metastatic malignant neoplasm involving the stomach. "IRX5 has been found to be downregulated in gastric cancer samples compared to adjacent tissues in several populations." (PMID 36980893, 2023).
Gastric tumor (1 paper, 2018). "Gastric tumor development in the small intestine in Irx5 transgenic mice." (PMID 29463648, 2018).
intestinal tumors (1 paper, 2018). "We also demonstrated that Irx5-Tg mice developed intestinal tumors that recapitulated some of the characteristics of ectopic epithelia found in Id2−/− mice." (PMID 29463648, 2018). "We found that 16% (n = 11/68) of Irx5-Tg mice older than 50 weeks developed a total of 13 intestinal tumors." (PMID 29463648, 2018).
Ito (1 paper, 2014). "Indeed the molecular basis of Ito is Kcnd2/Kv4.2 that has previously been claimed to be transcriptionally regulated by the miR-1 target Irx5 and to be at least in part responsible for cardiac conduction defects observed in miR-1-2 mutant mice." (PMID 25415383, 2014).
Kabuki syndrome (1 paper, 2016). Kabuki syndrome (KS) is a multiple congenital anomaly syndrome characterized by typical facial features, skeletal anomalies, mild to moderate intellectual disability and postnatal growth deficiency. "Our studies identified markedly reduced expression of PHKG1 in two Kabuki syndrome subjects and decreased expression of IRX5 in one subject." (PMID 27670201, 2016). "On the basis of these data, we speculate that KMT2D regulation of IRX5 and PHKG1 contributes to the pathogenesis of Kabuki syndrome." (PMID 27670201, 2016).
leukemia (1 paper, 2022). A malignant (clonal) hematologic disorder, involving hematopoietic stem cells and characterized by the presence of primitive or atypical myeloid or lymphoid cells in the bone marrow and the blood. "Screening of RNA-seq data from 100 leukemia/lymphoma cell lines showed overexpression of IRX1, IRX3, and IRX5 in megakaryoblastic and myelomonocytic AML cell lines, chosen as suitable models for studying the regulation and function of these homeo-oncogenes." (PMID 35328612, 2022).
metastatic cancers (1 paper, 2021). A carcinoma which has spread from the original site of growth to another anatomic site. "We also identified six genes (KHDRBS2, IQSEC1, ARHGEF1, ARID5A, IRX5, and TMC6) that were activated in metastatic cancers in two of the three cancer types and might be associated with metastatic traits." (PMID 34294701, 2021).
skin cutaneous melanoma (1 paper, 2023). "Analysis of IRX5 expression across the clinical stages of skin cutaneous melanoma indicates a statistically significant correlation between higher IRX5 expression and advanced pathological tumor stage." (PMID 37084727, 2023). "Higher expression of IRX1, IRX2, IRX3, IRX5, and IRX6 all display statistically significant unfavorable prognosis for skin cutaneous melanoma." (PMID 37084727, 2023).
synovial sarcoma (1 paper, 2006). "Additionally, many other genes that have been previously related to synovial sarcomas, such as the SSX4 gene, EGFR and SALL2, components of the retinoic acid pathway (CRABP1 and RARG) as well as retinoic acid induced genes (IRX5 and TGFβ2), were also included in this module." (PMID 16503973, 2006).
thyroid cancer (1 paper, 2024). "Next, we explored the possible mechanisms by which IRX5 affects the prognosis of thyroid cancer patients by GO/KEGG enrichment analysis, and further investigated the effect of IRX5 on immune infiltration of thyroid cancer." (PMID 38868535, 2024).
tumor (17 papers, 2014 to 2025). "However, the underlying mechanisms by which IRX5 promotes tumour cell proliferation and inhibits apoptosis remain unclear." (PMID 32153043, 2020). "The transcription factor iroquois homeobox 5 (IRX5) plays an essential role in HCC, whereas little is known about its exact functions and underlying mechanisms in tumour metabolism reprogramming." (PMID 40208102, 2025). "In the cell clusters collected from the lung (C2, C3, C12, C13, and C19), shared TFs among malignant and precancerous cells included LTF, IRX5, SIX1, and RUNX1, associated with tumor invasion and metastasis." (PMID 39872221, 2025). "Our results here suggest that promotion of DNA repair and suppression of apoptosis should be explored as mechanisms linking IRX5 to tumor progression." (PMID 37084727, 2023). "IRX5 is overexpressed in the majority of tumor types, although some tumor types have decreased IRX5 expression." (PMID 37084727, 2023). "Mice injected with IRX5‐silenced cells showed significantly decreased tumour growth compared to those injected with cells transfected with sh‐NC." (PMID 32153043, 2020). "IRX5 plays a different role in multiple cancers, contributing to the development of many tumours by acting as an important transcription factor regulating key regulatory genes that control cell growth, invasion, migration and apoptosis." (PMID 32153043, 2020). "As assessed by measurements of tumour volume and weight, the knocked down of IRX5 expression significantly inhibited overall tumour growth." (PMID 32153043, 2020). "The IRX5 transcription factor plays a different role in multiple cancers and contributes to the development of many tumours." (PMID 32153043, 2020). "Immunohistochemical (IHC) staining revealed that the IRX5 protein was differentially expressed between tumour tissues and their matched adjacent non‐tumour tissues." (PMID 32153043, 2020). "Mechanically, we identified that IRX5 overexpression expedites NF‐κB signalling pathway and ultimately promotes tumour growth." (PMID 29761910, 2018). "After 5 weeks of xenograft growth, immunohistochemical staining revealed that IRX5‐overexpressing groups showed higher IRX5 expression compared to tumours from the control group." (PMID 29761910, 2018). "The tumour cells proliferation was increased in tumours from the IRX5‐overexpressing groups and decreased in IRX5‐knockdown groups, as evidenced by the staining density of Ki‐67 positive cells." (PMID 29761910, 2018). "In accordance with our study, it has been reported that IRX5 play crucial effects in various tumour types." (PMID 29761910, 2018). "Several studies regarding the association of IRX5 with cancers have shown that depending on the type of cancer, IRX5 could act both in tumor-suppressing and tumor-promoting roles via the transforming growth factor beta signaling." (PMID 39132059, 2022). "In summary, our study demonstrated that IRX5 is a potential tumour promoter gene in HCC." (PMID 32153043, 2020). "However, strong immunoreactivity for IRX5 was detected in the cell nucleus and in the cytoplasm of the tumor tissues." (PMID 32153043, 2020). "Moreover, the in vivo studies also confirmed that knockdown of IRX5 suppressed tumour growth in nude mice, suggesting that IRX5 could potentially be applied in the treatment of HCC." (PMID 32153043, 2020). "Likewise, tumours from the IRX5‐overexpressing group displayed increased OPN expression." (PMID 29761910, 2018). "The upregulation of other homeobox transcription factors was also observed by us in cases of infratentorial tumor, which was shown to be connected with Iroquois homeobox transcription factors (IRX1, IRX2, IRX3, IRX5) and the PAX3 gene." (PMID 26497896, 2015). "Total IHC score of IRX5 in HCC tissues and non‐tumour tissues (n = 10, P < 0.01)." (PMID 32153043, 2020). "The CCV also contacts the IRX5/CRNDE bidirectional promoter; however, no eQTL for IRX5 or CRNDE or any other gene was detected in either normal or tumor tissues (at p < 5 × 10−4)." (PMID 31910864, 2020).
tumor (continued). "In summary, our study demonstrated that IRX5 is up‐regulated in TSCC cells and tissues, which functionally enhances TSCC cells proliferation, migration and invasion in vitro as well as in xenograft tumour model in vivo." (PMID 29761910, 2018). "Finally, studies in xenograft tumour model showed that IRX5 significantly enhanced OPN expression and promoted tumour growth." (PMID 29761910, 2018). "Of these genes, Pax3, Irx5, and Chl1 were also differentially regulated between the Olig2-compartments of BSG and CG suggesting that they represent biological differences within the tumor cells." (PMID 25330836, 2014). "The non‐tumour tissues showed weak or no expression of IRX5." (PMID 32153043, 2020).
cancer (15 papers, 2008 to 2025). A tumor composed of atypical neoplastic, often pleomorphic cells that invade other tissues. "Here, we first found that both IRX5 and HCC development are highly expressed; IRX5 accelerates de novo fatty acid synthesis and promotes cancer cell proliferation and progression." (PMID 40208102, 2025). "Although previous studies, primarily in cancer cells, have characterized the proliferative role of IRX5, little is known about its role in DNA damage." (PMID 37084727, 2023). "A few studies, primarily in cancer, have characterized the role of IRX5 in the cell cycle, apoptosis, and cell migration." (PMID 37084727, 2023). "Most of the validated genes, such as IL15, ITGAM, PDK4, and IRX5, have been implicated in AML progression and/or as survival predictors in several types of cancers." (PMID 31740623, 2019). "Although IRX5 may suppress tumorigenesis, multiple studies have found IRX5 to be upregulated in cancers, suggesting a pro-oncogenic role." (PMID 37084727, 2023). "Adjacent genes (RPGRIP1L, RBL2, IRX3, IRX5) regulated by FTO SNPs are also involved in the occurrence and progression of cancer in various ways." (PMID 33304380, 2020). "Here we delineated a new regulatory pathway in which IRX5 transcriptionally regulates OPN and thus, impacts cancer progression." (PMID 29761910, 2018). "Other members of the Iroquois (IRO/IRX) family, IRX1, IRX3 and IRX5 have been found differentially methylated and/or expressed between supratentorial and infratentorial PAs, suggesting that these genes may have an important role in specific location cancer development." (PMID 29568396, 2018).
infection (3 papers, 2013 to 2022). The state of being infected such as from the introduction of a foreign agent such as serum, vaccine, antigenic substance or organism. "IRX5 expression was quantitated by qRT‐PCR and Western blot analyses 48 hours post‐infection." (PMID 29761910, 2018). "Some studies have demonstrated that upon infection, H. pylori activates the expression of a number of genes such as CagA, AKT, TNF-α, ATF3, IRX5, IL-6 and IL-8." (PMID 24069310, 2013).
IRX5 also shares sentences with these, for which no sentence is quoted: acute lymphoblastic leukemia (2 papers); diabetes (2); hepatocellular carcinoma (2); renal cell carcinoma (2); adenoma (1); B-cell precursor acute lymphoblastic leukemia (1); colon adenocarcinoma (1); cryptorchidism (1); developmental delay (1); diabetic nephropathy (1); Failure to thrive (1); Genetic obesity (1); infratentorial tumors (1); Insulin resistance (1); Intellectual disability (1); lung carcinoma (1); lung squamous cell carcinoma (1); lymphoma (1); Micropenis (1); myopia (1); osteoporosis (1); ovarian carcinoma (1); papillary thyroid carcinoma (1); T-cell ALL (1); thyroid adenocarcinoma (1); type 2 diabetes (1); Wilms tumours (1).